UBAP2L (ubiquitin associated protein 2 like)
Description:
Recruits the ubiquitination machinery to RNA polymerase II for polyubiquitination, removal and degradation, when the transcription-coupled nucleotide excision repair (TC-NER) machinery fails to resolve DNA damage. Plays an important role in the activity of long-term repopulating hematopoietic stem cells (LT-HSCs) (By similarity). Is a regulator of stress granule assembly, required for their efficient formation. Required for proper brain development and neocortex lamination (By similarity).
Synonyms: KIAA0144; NICE4; NICE-4; NEDLBF
Tractability: PROTAC: ubiquitination databases record sites on it; its protein half-life has been measured.
Gene: Protein-coding gene on chromosome 1 (154,220,179 to 154,271,510, forward strand). Ensembl gene ENSG00000143569.
Subcellular location: Nucleus; Chromosome; Cytoplasm; Cytoplasm, Stress granule
Subcellular location (Human Protein Atlas): Cytosol; Nuclear speckles
Gene Ontology:
Molecular function: protein binding; RNA binding
Biological process: binding of sperm to zona pellucida; hematopoietic stem cell homeostasis; positive regulation of stress granule assembly; stress granule assembly
Cellular component: chromosome; cytoplasm; nucleus; PcG protein complex; cytoplasmic stress granule
Genetic constraint (gnomAD): Loss-of-function variants: 12 observed, 122.44 expected, observed/expected ratio (o/e) 0.098, 90% interval 0.062 to 0.16. The upper end of that interval is the gene's LOEUF score, 0.16, which puts it in group 1 of 6, group 1 being the genes least tolerant of losing a copy. Missense variants: 906 observed, 1,318.3 expected, observed/expected ratio (o/e) 0.69, 90% interval 0.65 to 0.73. Synonymous variants: 473 observed, 529.47 expected, observed/expected ratio (o/e) 0.89, 90% interval 0.83 to 0.96.
Homologues: Orthologues: guinea pig UBAP2L (98% identical), mouse Ubap2l (98% identical), rat Ubap2l (98% identical), macaque UBAP2L (98% identical), pig UBAP2L (96% identical), chimpanzee UBAP2L (95% identical), rabbit UBAP2L (88% identical), tropical clawed frog ubap2l (76% identical), zebrafish ubap2l (68% identical), Drosophila melanogaster lig (25% identical), Caenorhabditis elegans pqn-59 (17% identical). Paralogues in human: UBAP2 (47% identical).
Diseases named in the same sentence as UBAP2L in open-access papers:
UBAP2L is named in the same sentence as 42 diseases in open-access papers, as found by Europe PMC text mining. Sharing a sentence is not in itself a finding about the gene and the disease. The quoted sentences say what the papers report.
gastric cancer (8 papers, 2021 to 2025). A primary or metastatic malignant neoplasm involving the stomach. "Cells that cause stomach cancer proliferate and spread more quickly when exposed to ubiquitin-associated protein 2 like (UBAP2L)." (PMID 38313020, 2024). "The gain- and loss-of-function study of UBAP2L was performed in gastric cancer cells by using overexpression plasmids and small interfering RNA." (PMID 34823423, 2021). "GEPIA database analysis showed that the expression of ubiquitin-associated protein 2 like (UBAP2L) in gastric cancer specimens was significantly higher than that in non-tumor tissue, and its high expression is associated with poor survival of gastric cancer patients." (PMID 34823423, 2021). "Further, UBAP2L overexpression is considered a marker of poor prognosis in patients with gastric cancer, glioma, and cervical carcinoma." (PMID 37062825, 2023). "Previous studies have demonstrated that UBAP2L is an oncogene involved in various cancers, including glioma, gastric cancer, and uterine cancer." (PMID 37062825, 2023). "UBAP2L has been shown to be overexpressed in several tumors, such as liver carcinoma, breast cancer and gastric cancer." (PMID 35433677, 2022). "The inhibitory effect of miR-148b-3p on gastric cancer cell proliferation, migration, and invasion was neutralized by the overexpression of UBAP2L to some degree, which suggested that miR-148b-3p functioned, at least in part, by regulating UBAP2L." (PMID 34823423, 2021). "The expression of miR-148b-3p was negatively correlated with that of UBAP2L in gastric cancer samples." (PMID 34823423, 2021). "UBAP2L was identified as a target of miR-148b-3p, and their expression levels were negatively correlated in gastric cancer tissues." (PMID 34823423, 2021). "In order to investigate the effect of UBAP2L on the biological behaviors of gastric cancer cells, UBAP2L was silenced in AGS and NCI-N87 cells, and overexpressed in MKN-45 and Hs746T cells." (PMID 34823423, 2021). "According to the Gene Expression Profiling Interactive Analysis (GEPIA) database, UBAP2L mRNA levels were markedly higher in gastric cancer tissues than that in normal gastric mucosa tissues." (PMID 34823423, 2021). "Nude mice inoculated with UBAP2L-silenced gastric cancer cells generated smaller xenografted tumors in vivo." (PMID 34823423, 2021). "Real-time PCR and western blot results showed that UBAP2L expression was upregulated in gastric cancer cell lines." (PMID 34823423, 2021). "From these results, we demonstrated that UBAP2L induced activation of Wnt/β-catenin signaling in gastric cancer cells." (PMID 34823423, 2021). "Loss- and gain-of-function experiments demonstrated that silencing of UBAP2L inhibited proliferation, migration and invasion, and induced apoptosis of gastric cancer cells, and overexpression of UBAP2L played opposite roles." (PMID 34823423, 2021). "The expression of UBAP2L and miR-148b-3p was detected in 27 pairs of gastric cancer and para-carcinoma normal gastric mucosa tissues by real-time PCR." (PMID 34823423, 2021). "The overall survival of gastric cancer patients with low expression of UBAP2L was better than those with high expression." (PMID 34823423, 2021). "UBAP2L expression is reported to be increased in gastric cancer tissues in the database, and our data demonstrate its elevation in gastric cancer specimens and cell lines." (PMID 34823423, 2021). "Overall, our study indicates that UBAP2L is required to maintain malignant behavior of gastric cancer cells, which involves the activation of Wnt/β-catenin signaling pathway." (PMID 34823423, 2021).
gastric cancer (continued). "From the data in this study, we deduced that UBAP2L was required by gastric cancer cells to maintain their malignant behaviors, which involved the activation of Wnt/β-catenin signaling pathway." (PMID 34823423, 2021). "We demonstrate that UBAP2L is highly expressed in gastric cancer specimens and cell lines, and its overexpression aggravates the growth and metastasis of gastric cancer cells by activating Wnt/β-catenin signaling." (PMID 34823423, 2021). "Correlation analysis revealed that the expression of UBAP2L was negatively correlated with that of miR-148b-3p in gastric cancer tissues." (PMID 34823423, 2021). "Herein, to investigate the roles of UBAP2L and miR-148b-3p in gastric cancer, we detected their expression in clinical gastric cancer specimens and changed their expression in gastric cancer cells." (PMID 34823423, 2021). "UBAP2L promoted proliferation, migration, invasion and tumorigenesis, and suppressed apoptosis of gastric cancer cells." (PMID 34823423, 2021). "We found that UBAP2L was increased in gastric cancer specimens, and its expression was negatively correlated with that of miR-148b-3p." (PMID 34823423, 2021). "The levels of miR-148-3p were lower in AGS and NCI-N87 cells than that in normal human gastric mucosa cells and other human gastric cancer cells, which was opposite with the expression of UBAP2L." (PMID 34823423, 2021). "In our study, UBAP2L was demonstrated to be upregulated in gastric cancer tissues, and its overexpression facilitated cell proliferation, migration, invasion, and tumorigenesis in gastric cancer cells." (PMID 34823423, 2021). "The present study aims to investigate the roles of UBAP2L in gastric cancer cells and the regulation of miR-148b-3p on UBAP2L expression via experiments in vivo and in vitro." (PMID 34823423, 2021). "The results suggest that UBAP2L likely exerts its function in gastric cancer cells by orchestrating Wnt/β-catenin signaling." (PMID 34823423, 2021). "Similarly, UBAP2L was silenced by miR-148b-3p in gastric cancer cells leading to the same phenotypes as in NSCLC." (PMID 35794863, 2022). "In addition to HCC, the promotion of EMT by UBAP2L has also been reported in prostate, lung and gastric cancers." (PMID 35794863, 2022). "Ubiquitin-associated protein 2-like (UBAP2L) is highly expressed in various types of tumors and has been shown to participate in tumor growth and metastasis; however, its role in gastric cancer (GC) remains unknown." (PMID 35304439, 2022). "This study aims to investigate the role of UBAP2L in gastric cancer." (PMID 34823423, 2021). "We propose UBAP2L as a potential therapeutic target against gastric cancer." (PMID 34823423, 2021). "Moreover, the analysis from database showed the positive correlation between expression of UBAP2L and that of wnt/β-catenin downstream target genes, CCND1, AXIN2, and MYC in gastric cancer tissues, suggesting that UBAP2L activated this signaling." (PMID 34823423, 2021). "We propose UBAP2L as a potential target for therapeutic treatments against gastric cancer." (PMID 34823423, 2021). "Moreover, UBAP2L has been proposed as a potential therapeutic target for gastric cancer." (PMID 38893151, 2024). "In addition, mice injected with Ubap2l−/− A549 cells show less nodules in their lungs, lighter lungs and increased survival 3 weeks after injection in contrast to mice injected with Ubap2l+/+ A549 cells, while the opposite result is observed in gastric cancer when UBAP2L is overexpressed." (PMID 35794863, 2022). "However, the function of UBAP2L in gastric cancer awaits further investigation." (PMID 34823423, 2021). "In addition, UBAP2L activated Wnt/β-catenin signaling, and the persistent activation of β-catenin partly reversed the inhibitory effect of UBAP2L knockdown on malignant behaviors of gastric cancer cells." (PMID 34823423, 2021). "Thus, we demonstrate that UBAP2L may exert tumor-promoting function partly through Wnt/β-catenin signaling in gastric cancer." (PMID 34823423, 2021).
gastric cancer (continued). "The results demonstrated that the anti-tumor effect of UBAP2L knockdown was antagonized by overexpression of β-catenin, suggesting that silencing of UBAP2L may restrain proliferation, migration, and invasion of gastric cancer cells by deactivating Wnt/β-catenin signaling." (PMID 34823423, 2021). "Next, the expression levels of UBAP2L were determined in normal human gastric mucosa cell GES-1 and four human gastric cancer cell lines AGS, MKN45, Hs726T, and NCI-N87." (PMID 34823423, 2021). "Not surprisingly, UBAP2L has been proposed to activate the Wnt/β-catenin signaling cascade in gastric cancer cells, leading to the expression of downstream pathway targets, known to be implicated in tumorigenesis and metastasis." (PMID 35794863, 2022). "Additionally, the overexpression of β-catenin could not completely reverse the influence of the UBAP2L knockdown in gastric cancer cells, suggesting that β-catenin was not the sole pathway that mediated the function of the UBAP2L." (PMID 34823423, 2021).
breast carcinoma (7 papers, 2018 to 2024). "For example, ubiquitin-associated protein 2-like (UBAP2L) is the most significantly upregulated protein in ER + breast cancer tissue (fold change 5.696, P < 0.01)." (PMID 39004717, 2024). "Meta-analysis collectively revealed that increased UBAP2L mRNA expression was associated with breast cancer as compared with the normal breast tissue (gene median rank: 1413.0, P = 4.27E−5)." (PMID 29196913, 2018). "Notably, ZR-75-30 and T-47D cells exhibited relatively higher UBAP2L expression among the five breast cancer cell lines and thus were chosen for loss-of-function study." (PMID 29196913, 2018). "Consistently, UBAP2L depletion leads to an enrichment of G2/Mitotic (G2/M) population in HeLa cells, in ZR-75-30 and in T-47D breast cancer cells and in DU145 prostate cancer cells pointing to an important role of UBAP2L as a cell cycle regulator." (PMID 35794863, 2022). "We found the expression of UBAP2L was significantly up-regulated in breast cancer tissues and cell lines." (PMID 29196913, 2018). "The expression of UBAP2L was determined in breast cancer tissues and cell lines by Western blotting and Oncomine database mining." (PMID 29196913, 2018). "Cell proliferation was then determined on breast cancer cells after UBAP2L knockdown using MTT assay." (PMID 29196913, 2018). "Then the expression of UBAP2L was silenced using RNA interference and the effects of UBAP2L knockdown on breast cancer cell proliferation and cell cycle progression by MTT and colony formation assay, and Flow cytometry, respectively." (PMID 29196913, 2018). "The UBAP2L expression was analyzed in eight pairs of fresh breast cancer tissues and paired paracarcinoma tissues by Western blot." (PMID 29196913, 2018). "In summary, our results suggest that UBAP2L plays a critical role for the development of breast cancer." (PMID 29196913, 2018). "Further analysis showed UBAP2L mRNA expression in breast cancer containing ductal breast cancer and invasive breast cancer exhibited a significant difference as compared with the normal breast tissue (P < 0.01) in Ma Breast 4 and Zhao Breast datasets." (PMID 29196913, 2018). "Consistent with the findings in breast cancer tissues, the expression of UBAP2L protein was upregulated in breast cancer cell lines, including MCF-7, ZR-75-30, BT-474, T-47D and MDA-MB-468 compared with normal breast cell lines, MCF-10A." (PMID 29196913, 2018). "The UBAP2L expression level in breast cancer tissue was significantly upregulated than that in the paracarcinoma tissues (P < 0.001)." (PMID 29196913, 2018). "In the current study, UBAP2L was found to be significantly upregulated in breast cancer tissues and cell lines." (PMID 29196913, 2018). "Using Oncomine public database, total of five datasets were screened for comparison of the differentially expressed UBAP2L in breast cancer and normal tissues." (PMID 29196913, 2018). "Gene knockout experiments demonstrated that UBAP2L inhibition could impede cell proliferation and lead to cell cycle arrest at the G2/M phase, suggesting UBAP2L is a potential target for breast cancer treatment." (PMID 39004717, 2024). "UBAP2L has been reported to be highly expressed in multiple cancers, and knockdown of UBAP2L could suppress malignant behaviors in cancer cells, including breast cancer, hepatocellular carcinoma, and prostate cancer." (PMID 34823423, 2021). "Our results demonstrated that knockdown of UBAP2L inhibited breast cancer cells growth and proliferation, which might be ascribed to G2/M cell cycle arrest." (PMID 29196913, 2018). "In this study, the expression of UBAP2L was determined in breast cancer tissues and cells." (PMID 29196913, 2018). "UBAP2L knockdown impedes the breast cancer cell proliferation and colony formation might thought G2/M cell cycle arrest." (PMID 29196913, 2018). "Our findings suggest that UBAP2L plays an important role in breast cancer cell proliferation and might serve as a potential target for breast cancer treatment." (PMID 29196913, 2018).
breast carcinoma (continued). "Consistently, the mRNA expression of UBAP2L was found to be significantly upregulated in breast cancer tissues in these datasets, except for Finak Breast, which might be ascribed to different specimen collection, sample size and inclusion criteria." (PMID 29196913, 2018). "The role of UBAP2L in cancer biology will supply a potential therapeutic target for breast cancer." (PMID 29196913, 2018). "However, the biological function of UBAP2L in breast cancer has been largely uncovered." (PMID 29196913, 2018). "Thus, this study was designed to evaluate whether UBAP2L can serve as a potential molecular target for breast cancer therapy." (PMID 29196913, 2018). "However, the effect of UBAP2L expression on breast cancer biology remains largely uncovered." (PMID 29196913, 2018). "For instance, it has been observed that knockdown of UBAP2L increases p21 and decreases CDK1 and CyclinB1 expression in breast cancer cells." (PMID 35794863, 2022). "At molecular levels, knockdown of UBAP2L increased p21 expression, but decreased the expression of CDK1 and Cyclin B1 in breast cancer cells." (PMID 29196913, 2018). "In prostate, breast cancers and HCC, UBAP2L depletion leads to an accumulation of G2/M cell population, whereas it was shown to increase the G0/G1 cells rate in Glioma and colorectal carcinoma, suggesting that UBAP2L may act during several cell cycle stages." (PMID 35794863, 2022). "Ubiquitin-associated protein 2-like (UBAP2L) contains a ubiquitin-associated domain near its N-terminus, which has been demonstrated to be overexpressed in multiple tumors, including hepatocellular carcinoma and colorectal carcinoma but its role has not been well studied in breast cancer." (PMID 29196913, 2018).
hepatocellular carcinoma (5 papers, 2018 to 2025). A malignant tumor that arises from hepatocytes. "Recent studies have confirmed that UBAP2L function as an oncogene and is associated with various types of cancer, including prostate cancer, glioma, hepatocellular carcinoma (HCC), and colorectal carcinoma." (PMID 29196913, 2018). "Particularly in hepatocellular carcinoma, UBAP2L overexpression enhances malignant phenotypes, while PRMT1-mediated methylation establishes a dynamic equilibrium between pro-survival SG assembly and the oncogenic functions of methylated UBAP2L." (PMID 41029457, 2025).
Intellectual disability (4 papers, 2022 to 2026). "In contrast, in females, DAS gene networks, including Ubap2l, Pik3cd, and Meis2, were primarily associated with neuritogenesis, neuronal development, and intellectual disability." (PMID 40790242, 2025). "We report a new neurodevelopmental disorder (NDD) with common features of language problems, intellectual disability, and behavioral issues caused by de novo likely gene-disruptive variants in UBAP2L, which encodes an essential regulator of SG assembly." (PMID 35977029, 2022). "By clinical evaluation of our patients and previously reported cases with UBAP2L variants, we propose that intellectual disability, developmental delay (particularly in speech), infants’ feeding difficulties, behavioural abnormalities and seizures are the main clinical features of NEDLBF patients." (PMID 39720179, 2024). "The mechanism by which UBAP2L variants cause developmental delay, speech delay, mild to severe intellectual disability (ID), seizures, hypotonia, behavioural abnormalities, hypotonia, skeletal and facial abnormalities, and other clinical symptoms remains unclear." (PMID 39720179, 2024).
prostate carcinoma (4 papers, 2021 to 2024). A carcinoma that arises from epithelial cells of the prostate gland. "For example, UBAP2L, a regulator of multiple important homeostatic pathways including stress-response signaling, was observed to be hypermethylated among WTC-exposed breast and prostate cancers." (PMID 38131903, 2023). "The rearrangements of UBAP2L and EHMT1 have been reported in liver, lung, breast, ovary, and prostate cancer but not in hematological malignancies, and ABL1 or BCR has not been reported as their partner genes." (PMID 39596557, 2024).
colorectal cancer (3 papers, 2018 to 2023). A primary or metastatic malignant neoplasm that affects the colon or rectum. "For example, UBAP2L is upregulated and its knockdown inhibits tumorigenesis and metastasis in colorectal cancer." (PMID 29196913, 2018).